LINC01915 (long independently transcribed non-coding RNA 1915)
Gene: Long non-coding RNA gene on chromosome 18 (24,534,551 to 24,708,542, forward strand). Ensembl gene ENSG00000265485.
Diseases named in the same sentence as LINC01915 in open-access papers:
LINC01915 is named in the same sentence as 1 disease in open-access papers, as found by Europe PMC text mining. Sharing a sentence is not in itself a finding about the gene and the disease. The quoted sentences say what the papers report.
tumor (2 papers, 2022 to 2023). "Overexpression of LINC01915 in CRC cells inhibits tumor angiogenesis, CAF activation, and normal fibroblasts (NFs) uptake of tumor-derived extracellular vesicles (EVs)." (PMID 37234178, 2023). "The expression of LINC02257, LINC02188, MYOSLID, C6orf223, MYG1-AS1, and Lnc-SKA2-1 was upregulated in tumor samples, while the expression of LINC00702, LOC100129434, and LINC01915 was downregulated in tumor samples." (PMID 35846431, 2022).